MLLT3 (MLLT3 super elongation complex subunit)
Diseases named in the same sentence as MLLT3 in open-access papers (continued):
Sharing a sentence is not in itself a finding about the gene and the disease.
melanoma (continued). "We further predicted the potential miRNAs that could target MLLT3 mRNA to figure out how MLLT3 was silenced in melanoma." (PMID 39716999, 2025). "Overall, our results suggest that targeting MLLT3 may provide the basis for new treatment strategies for melanoma." (PMID 39716999, 2025). "In addition, to reveal the role of MLLT3 in melanoma stem cells, the expression of stemness‐related genes were evaluated in melanoma stem cells after MLLT3 overexpression or knockout." (PMID 39716999, 2025). "In conclusion, our study suggests that targeting MLLT3 may be an anti‐tumor strategy and a promising method for the treatment of melanoma." (PMID 39716999, 2025). "MLLT3 is a transcription factor that regulates the stemness and progression of melanoma." (PMID 39716999, 2025). "Moreover, we further detected MLLT3 expression on melanoma cell epithelial‐mesenchymal transition (EMT) and stemness by western blot assay." (PMID 39716999, 2025). "In addition, we found that knockout of MLLT3 increased the sphereforming ability of melanoma cells." (PMID 39716999, 2025). "Therefore, MLLT3 may be a promising therapeutic target for melanoma." (PMID 39716999, 2025). "We also detected the expression of MLLT3 in PIG‐1 cell and several types of melanoma cells including A375, HT‐144, WM‐115 and SK‐MEL‐2 by using qRT‐PCR." (PMID 39716999, 2025). "In TCGA‐SKCM, the expression of MLLT3 was low in melanoma tissues, and the OS, DSS (disease specific survival) and PFI (progression free interval) of melanoma patients with low expression of MLLT3 were poor." (PMID 39716999, 2025). "First of all, we did not use genetically engineered mice as animal models, and we still do not know the occurrence and development of melanoma in MLLT3 knockout mice." (PMID 39716999, 2025). "Next, by TCGA analysis, the expression of MLLT3 was not significantly correlated with HMGB1 in melanoma." (PMID 39716999, 2025). "All the mechanisms by which MLLT3 regulates melanoma have not been discovered, so we believe that MLLT3 plays an important role in regulating the stemness and progression of melanoma." (PMID 39716999, 2025). "We did not detect miR‐320c in melanoma tissues and excluded it, we next measured the effect of miR‐493‐3p, miR‐542‐3p and miR‐3922‐3p on MLLT3 expression by qRT‐PCR and western blot assays." (PMID 39716999, 2025). "In addition, the expression of MLLT3 was irrelevant with YBX1 in melanoma, indicating YBX1 was not regulated by MLLT3." (PMID 39716999, 2025).
osteosarcoma (1 paper, 2023). A usually aggressive malignant bone-forming mesenchymal neoplasm, predominantly affecting adolescents and young adults. "Among them, MLLT3, ATM/ATR, DDX10, CASP1 and BRD4 have been extensively studied and shown to be associated with pathogenesis or clinical outcomes in osteosarcoma." (PMID 37894336, 2023).
Pleural effusion (1 paper, 2025). The presence of an excessive amount of fluid in the pleural cavity. "Analysis of DEGs in Cycling GZMA and GZMA CD4 T cells from pleural effusion of HP and LCP revealed that seven transcription factors (MLLT3, KLF12, FOXP1, NFKB1, ZEB2, TOX, JAZF1) were upregulated in both cycling GZMA CD4 and GZMA CD4 cells in MPE of LCP." (PMID 40959273, 2025).
tumor (55 papers, 2011 to 2026). "Specifically, knockout of MLLT3 (AF9) in intestinal epithelial cells significantly increased tumour formation induced by AOM/DSS." (PMID 37565737, 2023). "Chromosome 9p contains numerous tumor-associated genes, such as PAX5 at 9p13.2, CDKN2A, CDKN2B, MTAP, IFN, MLLT3, PTPLAD2 at 9p21.3, and JAK2 at 9p24.1." (PMID 31168295, 2019). "A subcutaneous tumor formation model was used to detect the function of MLLT3 in vivo." (PMID 39716999, 2025). "MLL gene is made up of 14 exons, encoding the histone lysine methyltransferase whereby it is also called KMT2A, which harbors powerful transforming potential associated with neoplastic diseases assisted by specific partners, such as AF9 (MLLT3), AF4, and ENL (MLLT1)." (PMID 34540702, 2021). "While a direct involvement of the cancer-related oncogenes ALK in 2p23.2, MLLT3 in 9p21.3, and BCL2 in 18q21.33 could be excluded, loss of two tumor suppresser gene loci in 9p21 and in 13q14 was found." (PMID 25374696, 2014). "Additional amplification of WT1, ERC1, ASIC2 and MTCP1 and deletion of CDKN2A and MLLT3 were found in recurring MFS (case 8b) but not in the original tumor (case 8a)." (PMID 38791144, 2024). "Interestingly, although the breakpoints for these losses are different in each tumor, they all occur in a narrowed region around CDKN2A/2B genes, and for three tumors the breaks occurred in the MLLT3 gene." (PMID 33963205, 2021). "Interestingly, expression of most of the fusion partners including the high‐frequency partners like AFF1, MLLT1, MLLT3, MLLT10, ELL, and MLLT4, were positively correlated with MLL1 expression irrespective of the tumor type." (PMID 30548174, 2019).
cancer (37 papers, 2006 to 2025). A tumor composed of atypical neoplastic, often pleomorphic cells that invade other tissues. "In addition to the enrichment of guides targeting TM9SF2, LAPTM4A, and genes related to sphingolipid biosynthesis, our analysis detected enrichment for guides targeting several genes associated with cancer and cell proliferation (MLLT3, TFAP4, ZNF217, and DUSP6) (35, –, 38)." (PMID 29921669, 2018). "For instance, nine of our candidate cancer genes were also contained in the Cancer Gene Census list, which comprises 487 genes causally linked to cancer, representing a highly significant enrichment (Abl2, Braf, Fbxw7, Foxp1, Ipo11, Mllt3, Fas, Pten, and Nf1; p<0.0002, Fisher’s exact test)." (PMID 23940809, 2013). "MLLT3 has primarily been studied in cancer, where its truncation and fusion with MLL1 leads to aberrant H3K79 methylation, dysregulating the JNK and WNT pathways." (PMID 39804120, 2025). "Cancer subtypes with G12/13 prevalence in the concordantly upregulated axes are characterized by mutations of the KRAS, PIK3CA, and MLLT3 oncogenes." (PMID 38723607, 2024). "With regard to CNS, the candidate gene MLLT3 (MLLT3 super elongation complex subunit) was also identified for CNS, which is involved in the transcriptional misregulation mechanism of cancer (String)." (PMID 34205623, 2021). "These eight transcripts were linked to the following cancer‐related genes: TRIM33, USP6, PRDM16, SETD1B, MLLT3, KEAP1, CHD2, and DCAF12L2." (PMID 32821278, 2020). "After multivariate cox’s model filtering, we identified 4 mRNAs (MLLT3, CEBPA, HIST2H3C and AFF1) in ‘Transcriptional misregulation in cancer’ pathway were independently associated with prognosis." (PMID 30181715, 2018). "By overlapping with TCGA RNA expression profile and pan‐cancer analysis, we found oncogene MAGEA1 was a potential target of MLLT3." (PMID 39716999, 2025). "Some of the most prevalent included known pediatric cancer fusions RUNX1::RUNX1T1 (15% AML participants), KMT2A::MLLT3/MLLT10 (12% AML), TCF3::PBX1 (4.4% ALL), and ETV6::RUNX1 (2.4% ALL)." (PMID 37323575, 2023). "Copy number deletions of cancer suppressor genes (including CDKN2A/B, FOCAD, NF2, etc.)are always accompanied by adjacent functional genes (including MTAP, MLLT3, etc.)deletion that synergistically contributes to oncogenesis." (PMID 37033966, 2023). "9p21.3 was the most significantly deleted segment in AK and harbors 10 cancer genes, including CDKN2A, JAK2, and MLLT3." (PMID 33482222, 2021). "Among them, the following well-known cancer genes were found: MET, CDK4, MDM4, EGFR and PIK3CA (amplifications), and CDKN2A, MLLT3, HRAS, CARS and NF1 (deletions)." (PMID 23408991, 2013). "Notably, six genes—MLLT3, MEIS1, PBX1, PBX3, HOXA10, KMT2A—were found to play a role in transcriptional dysregulation in cancer." (PMID 35743243, 2022). "Some cancer genes also show negative selection in cancer genomes, such as the oncogene MLLT3 (CN/CS = 0.11, p = 3.14 × 10–44, FDR = 5.52 × 10–41)." (PMID 28938601, 2017). "We also found that six genes (TBP, EP400, DSPP, MUC21, MLLT3, and MUC2) were under negative selection in more than five cancer types." (PMID 28938601, 2017).
MLLT3 also shares sentences with these, for which no sentence is quoted: myeloid leukemia (18 papers); acute lymphoblastic leukemia (12); myeloproliferative neoplasm (7); acute monoblastic leukemia (5); infection (4); lymphoma (4); myelodysplastic syndrome (4); chronic myeloid leukemia (3); colorectal cancer (3); epilepsy (3); monocytic leukemia (3); T-cell acute leukemia (3); Acute myelomonocytic leukemia (2); blood cancer (2); childhood leukemia (2); colon cancer (2); Intellectual disability (2); lung carcinoma (2); lymphocytic leukemia (2); myeloid malignancies (2); neurodevelopmental disorder (2); prostate carcinoma (2); sarcoma (2); T-lymphoblastic lymphoma (2); acute erythroid leukemia (1); acute megakaryoblastic leukemia (1); asthma (1); autism (1); B-cell acute lymphoblastic leukaemia (1); B-cell acute lymphoblastic leukemia (1).
A further 38 diseases each share a sentence with MLLT3 in 1 paper.